RNU6-518P (RNA, U6 small nuclear 518, pseudogene)
Gene: Small nuclear RNA gene on chromosome 17 (58,835,899 to 58,835,994, forward strand). Ensembl gene ENSG00000251865.
Homologues: Orthologues: chimpanzee U6 (99% identical), macaque U6 (91% identical). Paralogues in human: RNU6-47P (83% identical), RNU6-116P (82% identical), RNU6-33P (82% identical), RNU6-698P (82% identical), RNU6-1 (81% identical), RNU6-1175P (81% identical), RNU6-11P (81% identical), RNU6-15P (81% identical), RNU6-188P (81% identical), RNU6-2 (81% identical), RNU6-378P (81% identical), RNU6-37P (81% identical), and 1287 more.